PKM (pyruvate kinase M1/2)
Diseases named in the same sentence as PKM in open-access papers (continued):
Sharing a sentence is not in itself a finding about the gene and the disease.
cancer (continued). "By releasing miR-122, cancer cell-derived exosomes downregulate PKM and GLUT1 in neurons, astrocytes, and fibroblasts, therefore reducing the glucose consumption in mice brains and lungs." (PMID 36012638, 2022). "It is worth noting that hnRNPA1 has been shown to alter aerobic glycolysis of cancer cells by directing the alternative splicing of pyruvate kinase (PKM)." (PMID 35879279, 2022). "Low c-Myc inhibits uncontrolled DNA synthesis associated with cancer and thus lowers the expression of PGM, PKM, and LDHA, and eventually downregulates carbon consumption needed to sustain malignancy." (PMID 36364182, 2022). "As a result, metabolic regulators such as PKM have emerged as part of the focus of “anti-Warburg” drug development to fight cancer." (PMID 35987203, 2022). "Pyruvate kinase (PKM) is an important molecule in cellular metabolism, and its splice isomers, PKM1 and PKM2, are expressed in the adult and embryonic stages, respectively; PKM2 is aberrantly expressed in a variety of cancers." (PMID 36591484, 2022). "In cancer cells, the pyruvate kinase muscle isoenzyme (PKM) plays a significant role in cancer cell metabolism to adapt to a new ambience." (PMID 33958005, 2021). "The selective expression of an isoform of the glycolytic enzyme pyruvate kinase M (PKM) is related to the metabolic phenotype of cancer cells." (PMID 34930376, 2021). "Among them, PKM2 shows the highest expression level in all the cancer types followed by PKM-093 and PKM-883, and it represents ~95% of PKM mRNA expression." (PMID 33478099, 2021). "We employed systems biology methods to reveal prognostic value and potential biological functions of PKM transcripts in different human cancers." (PMID 33478099, 2021). "Cancer cells reprogram their cellular metabolism by regulating alternative splicing of pyruvate kinase muscle (PKM) isoforms." (PMID 33863392, 2021). "By contrast, pyruvate kinase L/R (PKLR), an isozyme of PKM, had a high level of differential gene expression in both cancers." (PMID 34137202, 2021). "There are two mutually exclusive PKM isoforms: PKM2 is upregulated in cancer, promoting aerobic glycolysis, whereas PKM1 is expressed in most normal tissues, promoting oxidative phosphorylation." (PMID 33923658, 2021). "SAM68 drives cancer metabolism by mediating alternative splicing of pyruvate kinase (PKM) pre-mRNAs, and promoting the formation of PKM2." (PMID 33537092, 2021). "We discovered three poorly studied alternatively spliced PKM transcripts that exhibited opposite prognostic indications in different human cancers based on integrative systems analysis." (PMID 33478099, 2021). "A key oncoprotein pyruvate kinase M (PKM) has a vital role in the metabolic adaptations of cancer cells." (PMID 34769743, 2021). "Together, these results suggest that SRSF10 promotes the cancer-specific isoforms of genes like PKM and BCLx thus play a crucial role in HNC." (PMID 34616729, 2021). "We integrated YAP1 and PKM coexpression genes in the Cancer Cell Line Encyclopedia (CCLE) dataset and separately defined them as the YAP1 and PKM signature." (PMID 34345207, 2021). "This suggests that tumor suppressor SMAR1 inhibits tumor cell metabolism and tumorigenic properties of cancer cells via regulation of PKM alternative splicing." (PMID 33863392, 2021). "For example, the PKM gene is a pyruvate kinase enzyme with an essential role in metabolism and is important in the growth of cancer cells." (PMID 33651795, 2021). "In order to explore the function of the prognostic transcripts identified in this study, we designed vectors and transfected to PC3 cancer cell lines to over-express PKM-093 and PKM-883." (PMID 33478099, 2021). "At the transcript level, we found six of these transcripts, including PKM1, PKM2, PKM-609, PKM-093, PKM-883, and ENST00000562997, are significantly associated with patients’ survival outcome in at least one cancer." (PMID 33478099, 2021).
cancer (continued). "We also found that the expression of PKM indicated an opposite survival outcome of patients compared to that of its transcripts in multiple cancer types." (PMID 33478099, 2021). "Highly proliferating cancer cells exhibit the Warburg effect by regulation of PKM alternative splicing and promoting the expression of PKM2." (PMID 33863392, 2021). "Nine out of 45 and 21 out of 84 genes for LUAD and LUSC, respectively, with high levels of differential expression based on cancer and healthy samples in TCGA database; the other genes, such as PKM and PTDSS1, have low levels of differential expression." (PMID 34137202, 2021). "Pyruvate kinase muscle type (PKM) is a key enzyme in glycolysis and plays an important oncological role in cancer." (PMID 33478099, 2021). "The M2 isoform of pyruvate kinase (PKM2) (also named PKM, PK3, THBP1), an essential enzyme involved in glycolysis, is known to mediate the conversion of glucose to lactate in cancer cells under normoxic conditions." (PMID 34285141, 2021). "Among them, the mRNA expression of transcript encoding PKM2 exhibited a very similar prognostic indication to PKM in all cancer types since it dominates the mRNA expression of PKM." (PMID 33478099, 2021). "In this study, we only focus on the expression of different alternatively spliced transcripts of PKM and explore the potential biology functions and prognostic effects in different cancers." (PMID 33478099, 2021). "PKM is highly upregulated during tumorigenesis and functions as a metabolic regulator of the glycolytic pathway in many cancer cells, channelizing glycolytic intermediates away from the respiratory chain towards anaerobic glycolysis." (PMID 34947512, 2021). "Several studies have been performed for studying the functional role of PKM in cancer metabolism, mainly focusing on PKM1 and PKM2 isoforms." (PMID 33478099, 2021). "Previous studies have shown that hnRNP A1 expression is regulated by c-myc at the transcriptional level and that the c-myc-hnRNP A1 pathway regulates PKM splicing to promote cancer aerobic glycolysis." (PMID 32754263, 2020). "PKM is a glycolytic enzyme that converts phosphoenolpyruvate to pyruvate and is involved in cancer cell proliferation and metabolism." (PMID 33050576, 2020). "ZFP91 suppresses cancer metabolism reprogramming and progression by ubiquitinating and degrading hnRNP A1 to regulate PKM splicing in HCC cells." (PMID 32754263, 2020). "In cancer, a key cancer metabolic reprogramming-associated enzyme is pyruvate kinase muscle (HGNC gene symbol: PKM; EC 2.7.1.40)." (PMID 32992783, 2020). "The CCK8 assays revealed that silencing of miR-330 and overexpression of PKM significantly rescued the suppression of cancer cell growth induced by the decreasing of CAF-secreted exosomal SNHG3 in MD-MBA-453 cells." (PMID 31956955, 2020). "Cancer cells commonly upregulate the alternative splicing of pyruvate kinase muscle (PKM2) from PKM pre-mRNA to enable further aerobic glycolysis." (PMID 32244756, 2020). "We found that ZFP91 suppresses cancer aerobic glycolysis in HCC cells by regulating the alternative splicing of glycolytic enzyme PKM pre-mRNA through hnRNP A1." (PMID 32754263, 2020). "Very importantly, PKM is universally expressed in cancer and play a pivotal role in maintaining the metabolic program during cancer progression." (PMID 32984260, 2020). "Genes from the enriched metabolic pathways were intersected, and only PKM, an important molecule for glycolysis metabolism of cancer, was found to be overlapped." (PMID 32296635, 2020). "As shown by Prakasam, cancer cells express both PKM isoforms which interact to generate heterotetrameric cross-oligomers and jointly contribute to the overall pyruvate kinase activity in a cancer cell." (PMID 32121279, 2020). "Pyruvate kinase muscle isozyme M2 (PKM2), one isoform of PKM, is an important glycolytic enzyme participating in the final step in glycolysis, which was essential in cancer metabolism and proliferation." (PMID 31956955, 2020).
cancer (continued). "The splicing of PKM is regulated by the cancer gene Myc and by heterogeneous nuclear ribonucleoproteins (hnRNPs)." (PMID 32992783, 2020). "Perhaps related to this activity of PKM, it has been reported that cancer stem cells play an important role in metastasis." (PMID 33615312, 2020). "The abnormal expression of PKM promoted cancer growth, invasion, and metastasis by governing aerobic glycolysis and induced cancer treatment resistance." (PMID 33344071, 2020). "PKM is a rate-limiting enzyme in the final step of glycolysis, that is considered as one of the metabolic hallmarks of cancer." (PMID 33344071, 2020). "Pyruvate kinase (PKM) functions as a key glycolytic enzyme which converts phosphoenolpyruvate to pyruvate, and the M2 isoform of pyruvate kinase (PKM2) is crucial for cancer cell metabolism, proliferation, and metastasis." (PMID 31956955, 2020). "The pyruvate kinase embryonic isozyme M2 (PKM2), resulting from alternative splicing of PKM pre-mRNA, is a promoter of Warburg effect and it is over-expressed in different types of cancer." (PMID 31366176, 2019). "Pyruvate Kinase M2 (PKM2) is an oncofetal isoform generated as a result of alternative splicing of the PKM mRNA transcript exhibit low basal activity and thus is a key player in regulating the glycolytic flux contributing to cancer progression." (PMID 30735509, 2019). "Mammals have four PK isoforms (L, R, M1 and M2) among these pyruvate kinases (muscle), PKM1 and PKM2, are alternative spliced products of PKM and overexpressed in cancers." (PMID 31638999, 2019). "The induction of switching of a PKM isoform from PKM2 to PKM1 in various cancer cells by ectopic expression of these miRNAs supports our opinion." (PMID 29695138, 2018). "Inhibition of DNA methylation impairs binding of BORIS to PKM exon 10 and promotes the switch from the cancer-specific PKM2 to the PKM1 isoform." (PMID 30319972, 2018). "To clarify the role of the splicer in cancer metabolism, we examined how PKM isoform switching was induced by silencing each of the PKM splicer cording genes." (PMID 30279379, 2018). "In conclusion, the plasticity in the regulation of the PKM gene expression is exploited by cancer cells to promote their growth and metabolism." (PMID 29468140, 2018). "Another example is RBM4, a splicing factor that links alternative splicing of PKM transcripts to cell differentiation programs and cancer by antagonizing the function of PTB/hnRNPI." (PMID 30319972, 2018). "The hnRNPs’ selectively bind the sequence flanking exon 9 in PKM pre-mRNA to repress its inclusion to the mature mRNA, and thus, indirectly facilitating the inclusion of exon 10 into the mature mRNA, resulting in the expression of PKM2 mRNA in cancer cells." (PMID 29468140, 2018). "PTBP1 promotes expression levels of cancer-dominant PKM2 by including exon 10 of the PKM gene to produce this isoform." (PMID 28380435, 2017). "PKM2 is encoded by the PKM gene and is expressed in embryonic cells, adult stem cells, and cancer cells." (PMID 28978113, 2017). "For instance, PKM2 is the embryonic splice-variant of the PKM gene that promotes aerobic glycolysis and sustains cancer cells proliferation and metabolism." (PMID 28137272, 2017). "Understanding the regulation of PKM pre-mRNA alternative splicing is of great importance for developing cancer therapy." (PMID 28086949, 2017). "Several other compounds activating PKM activity in cancer cells were recently tested as potential anti-cancer drugs." (PMID 29262552, 2017). "Inhibition of serine to glycine conversion can increase lactate levels and toxicity in cancer cells due to PKM activity stimulation as well as inhibit folate-driven ETC activity and purine biosynthesis." (PMID 29262552, 2017). "Contrary to our findings, recent reports claimed the inhibitory effect of naphthoquinonic compound shikonin on PKM activity in cancer cells." (PMID 29262552, 2017).
cancer (continued). "In the case of tumors originating from differentiated cells, high levels of PKM2 in tumor or cancer initiating cells are attributed to the switch of PKM gene splicing from PKM1 to PKM2." (PMID 28978087, 2017). "Earlier, we found that PTBP1, a major splicer of the PKM gene, is a gene responsible for maintenance of the cancer specific energy metabolism and that it is frequently overexpressed in clinical tumor samples." (PMID 28106737, 2017). "Splicing repressors hnRNPA1 and hnRNPA2 have been found to regulate PKM alternative splicing in cancer cells." (PMID 28105922, 2016). "PKM isoforms are targeted by miR-124, miR-137 and miR-340; therefore, these miRNAs impair cancer growth by counteracting Warburg’s effect by modulating the PKM isoform ratio." (PMID 27213336, 2016). "Splicing of the mutually exclusive PKM exons 9 and 10 determines the metabolic switch towards lactate production and the Warburg effect in cancer cells." (PMID 27380775, 2016). "Alternative splicing of pyruvate kinase M (PKM) pre-mRNA generates the PKM2 isoform in all cancer cells." (PMID 28105922, 2016). "Strikingly, tissue-specific isoform switch and DNA hypomethylation of the pyruvate kinase PKM gene in human cancers." (PMID 26376677, 2015). "Here, we demonstrated that the switching of PKM isoform expression from PKM1 to PKM2 during cancer development occurred only in limited types of tumors, as based on PKM expression profiles in their normal tissues." (PMID 25721733, 2015). "PKM2 is one of the splicing variants from PKM gene, expressed in development and most cancers, and plays a central role in tumorigenesis." (PMID 25773278, 2015). "The ability of EGFR activation to modulate the metabolism of cancer cells requires the expression of the PKM2 splicing isoform of pyruvate kinase M (PKM), the enzyme that catalyzes the final step of glycolysis." (PMID 24078813, 2013). "Another example of PTB-hnRNP association has been reported for PKM encoding pyruvate-kinase-M, where PTB and hnRNPs A1/A2 cooperate in excluding exon 9 to increase lactate production in cancer cells." (PMID 24121633, 2013). "The low-active splice form of the PKM-type pyruvate kinase (PKM2) is present at higher concentration in cancers compared to matched control tissue." (PMID 21907146, 2011). "We found that PKM2 was the predominant PKM isoform in all human cancer cell lines, which is in agreement with the earlier results obtained by Western blotting." (PMID 21789790, 2011). "In light of these results it has to be considered that the high concentrated PKM2, although possessing a lower catalytic activity as PKM1, is responsible for most PKM activity in most healthy and cancer tissue." (PMID 21789790, 2011). "Alternative splicing of PKM results in the production of two variants: PKM1, which includes exon 9 of the PKM gene and is expressed in the majority of adult tissues, and PKM2, which contains exon 10 and is primarily found in fetal tissues and cancer cells." (PMID 39988592, 2025). "Moreover, the use of ASO small nucleic acid drugs to modulate the splicing pattern of PKM pre-mRNA and facilitate the production of PKM1 instead of PKM2 in cancer cells can effectively impede cell proliferation and delay tumor formation." (PMID 40137167, 2025). "It is important to clarify the molecular mechanisms of PKM proteoforms in cancer metabolism." (PMID 40137167, 2025). "Previous studies have suggested varying functions of the PKM isoforms in both AD and cancer." (PMID 40667488, 2025). "Furthermore, phosphorylation at Ser6 can modulate PKM splicing, thereby exerting an impact on glucose metabolism reprogramming in cancer cells." (PMID 39366930, 2024). "In cancer, Sam68 was shown to promote a prooncogenic energy metabolism switch in lung adenocarcinoma by influencing alternative splicing of Pyruvate Kinase Muscle (PKM)." (PMID 37792222, 2024). "A differential expression of pyruvate kinase muscle (PKM) isoforms is also present in cancer." (PMID 39194522, 2024).
cancer (continued). "PKM is a key enzyme for glycolysis, and the PKM2 isoform is one of the main players in switching between oxidative and glycolytic metabolism associated with the Warburg effect in cancer cells." (PMID 38534317, 2024). "Therefore, identification of the factors and mechanisms underlying PKM alternative splicing, resulting in the PKM2-mediated Warburg effect, is crucial for overcoming the current challenges in cancer treatment." (PMID 36810109, 2023). "The role of PTBP1 in PKM splicing is already known in several cancer types." (PMID 36508323, 2023). "Several studies showed that PKM plays an important role in regulating glycolysis in cancers." (PMID 39188277, 2023). "While demonstrating that tumor initiation does not require PKM2, this study and others support the hypothesis that the loss of enzymatically active PKM function, such as PKM1 downregulation, is essential for proliferating cancer cells." (PMID 35681470, 2022). "Tyr-105 phosphoryl form of PKM2 prevents the active PKM tetramer form in cancer cells." (PMID 36077431, 2022). "The alternatively spliced PKM-type pyruvate kinase (PKM2) form is largely expressed in cancers." (PMID 36077431, 2022). "We next to determine whether RGGMUT-hnRNP A1 affects PKM alternative splicing, cancer phenotypes, and cellular glycolysis." (PMID 33564070, 2021). "It has been shown that PTB is involved in PKM gene alternative splicing regulation in cancer cells." (PMID 34646373, 2021). "Thus, mRNA expression of PKM has ambiguous indication of patients’ survival in different cancer types." (PMID 33478099, 2021). "PTB plays a role in regulating PKM alternative splicing in cancer cells." (PMID 34646373, 2021). "Combined with the survival analysis results, we speculated that SERPINC1 and PKM play important roles, namely, cancer-suppressing and cancer-promoting functions, respectively, under hypoxia exposure." (PMID 33690171, 2021). "Therefore, we used the recently developed base editors, ABEmax‐NG18 and BE4max19 with optimized codons and expanded editing scope, to investigate the isoform‐specific functions of PKM in cultured cancer cells and zebrafish embryos." (PMID 34240779, 2021). "Providing that memantine decreased the master oncogenic regulators like HIF1A, B-catenin and PKM, our results conclude that memantine could be used in targeting cancer cell metabolism." (PMID 34121969, 2021). "PKM has also been known to be related to the invasiveness of cancers." (PMID 33937086, 2021). "The mRNA expression of the PKM indicated opposite survival outcomes in different cancer types." (PMID 33478099, 2021). "Besides, PKM is essential in the metabolic reprogramming, the regulation of growth, apoptosis, and metastasis of cancer cells." (PMID 31956955, 2020). "Indeed, LDHA, PKM, and IDH2 are well-known players in the upregulation of cancer metabolism which are strongly associated with aggressive and invasive behavior of tumors and shortened patient’s survival." (PMID 33311447, 2020). "Therefore, the exosomal transport of SNHG3 from CAFs to neighboring cancer cells modulates the miR-330-5p/PKM axis and then stimulates cell proliferation and metabolism reprogramming in breast cancer cells." (PMID 33050576, 2020). "Also, pyruvate kinase muscle 2 (PKM2), the alternative splicing form of PKM that enables exacerbated aerobic glycolysis in cancer cells, has been shown to directly promote the expression of PD-L1 in cancer cells." (PMID 32630618, 2020). "One splicing target of hnRNP in cancer cells is Pyruvate Kinase Muscle (PKM)." (PMID 32466553, 2020). "PKM is essential for aerobic glycolysis, a dominant metabolic pathway utilized by cancer cells." (PMID 30916466, 2019). "Furthermore, the differential splicing of PKM, another unique feature different from regular pathways, plays a novel role in cancer cell metabolism." (PMID 31654067, 2019).